TUBB3 (tubulin beta 3 class III)
Diseases named in the same sentence as TUBB3 in open-access papers (continued):
Sharing a sentence is not in itself a finding about the gene and the disease.
prostate carcinoma (12 papers, 2017 to 2023). A carcinoma that arises from epithelial cells of the prostate gland. "SRC kinase-mediated tyrosine phosphorylation of TUBB3 was demonstrated to regulate mitotic spindle dynamics in prostate cancers." (PMID 37466845, 2023). "There is also evidence that androgens modulate TUBB3 expression: in prostate cancer cells and patient tumors, androgen ablation correlates with high TUBB3 levels." (PMID 37065867, 2023). "Here, we report, for the first time, that TUBB3 is phosphorylated at Tyrosine 340 (Y340) by c-SRC in prostate cancer cells." (PMID 35631517, 2022). "Recent studies have reported that TUBB3 overexpression is involved in docetaxel (DTX) resistance in prostate cancer (PCa)." (PMID 31412591, 2019). "A similarly strong prognostic role has recently been described for aberrant βIII-tubulin (TUBB3) expression in prostate cancer." (PMID 30823906, 2019). "It would be interesting to study the relationship between expression of proteins related to the microtubules system - such as MAPT and TUBB3 - and response to taxanes in prostate cancer in clinical trials." (PMID 30823906, 2019). "Furthermore, we report here for the first time that TUBB3 is phosphorylated at tyrosine by active Src kinase in prostate cancer cells, specifically at tyrosine 340 (Y340)." (PMID 35631517, 2022). "Besides, TUBB3 expression among diverse histological subtypes of prostate cancer is also worth investigating." (PMID 34318630, 2021). "Besides those widely recognized biomarkers, TUBB3 is likely to participate in a more intricate and extensive network within the prostate cancer progression and drug resistance mechanism." (PMID 34318630, 2021). "Therefore, we also determined the relationship of ERRα and TUBB3 by bioinformatics analysis using TCGA prostate cancer data containing 551 samples." (PMID 33014785, 2020). "Moreover, downregulation of TUBB3 contributed to increased PTEN expression, which was beneficial for re-sensitizing docetaxel-resistant prostate cancer cell lines to cabazitaxel." (PMID 35173149, 2022). "In the current study, we characterized the regulation of β-tubulin isoform TUBB3 by SRC-mediated tyrosine phosphorylation and its role in the regulation of subcellular localization and protein stability of TUBB3 and mitotic spindle stability in prostate cancer cells." (PMID 35631517, 2022).
neuroblastoma (10 papers, 2014 to 2022). Neuroblastoma (NB) is the most common solid, extracranial childhood tumor. "Initially, we tested five different Tubb3 mi-RNA knockdown constructs (miRNA-1 to 5), compared to a scrambled control (miRNA-scr), following transfection in neuroblastoma N2a cells." (PMID 36309617, 2022). "To determine whether the loss of TREX1 affects neuronal development, we knocked down the TREX1 gene in SH-SY5Y neuroblastoma cells and examined neuronal differentiation by immunocytochemical analysis of neuron-specific markers, such as TUBB3, MAP2, and NF-L." (PMID 34997539, 2022). "Whether NGFR upregulation is instrumental and causal for the enhanced expression of NTRK2, NEFL, TUBB3, and MAP2 that we observe in the L-AN-5 neuroblastoma system, remains to be investigated." (PMID 33174841, 2020). "In addition, we tested the HMEJ-based method in N2a cells (a mouse neuroblastoma cell line) at the Actb, Tubb3 and Rosa26 loci, and also observed that HR- and HMEJ-based methods showed higher knock-in efficiency than NHEJ- and MMEJ-based methods." (PMID 28524166, 2017). "Because POU5F1+ germ cells both in ovaries and adrenals seem to express TUBB3 as well, it may be important to investigate the expression of additional markers to exclude a potential link between neuroblastoma and ‘adrenal’ germ cells." (PMID 26834021, 2016). "Here, we also report an increase in TUBB3, MAP2, TH and DAT levels during neuroblastoma SH-SY5Y rho0 cell differentiation." (PMID 31717322, 2019).
brain malformations (9 papers, 2015 to 2025). "TUBB3 is linked to diseases such as cortical dysplasia, which is complex, with other brain malformations." (PMID 39129166, 2025). "TUBB3 is a neuron-specific tubulin isotype, and TUBB3 mutations typically cause structural brain malformations and/or congenital fibrosis of the extraocular muscle 3 (CFEOM3), an axon guidance disorder affecting the muscles that control the eye." (PMID 36875768, 2023).
congenital fibrosis of the extraocular muscles (8 papers, 2017 to 2025). "TUBB3 is a gene associated with congenital fibrosis of extraocular muscles (CFEOM3A), a disorder affecting the growth and guidance of ocular motor nerves." (PMID 39129166, 2025). "TUBB3 is originally identified as a genetic cause of congenital fibrosis of the extraocular muscles (CFEOM), a complex dysmotility disorder characterized by ptosis and strabismus, with or without additional neurological findings." (PMID 31355196, 2019). "Congenital fibrosis of the extraocular muscles type 1 (CFEOM1) is known to be caused by mutations in KIF21A or TUBB3 or other known genes (SALL4, CHN1, HOXA1)." (PMID 29110737, 2017). "In 2010, human heterozygous TUBB3 missense variants were reported to cause isolated and syndromic congenital fibrosis of the extraocular muscles (CFEOM), a congenital paralytic eye movement disorder." (PMID 37600020, 2023). "Congenital fibrosis of the extraocular muscles (CFEOM) affects cranial nerves 3 and 4 and is caused by autosomal dominant missense variants in KIF21A, TUBB3, TUBB2B or TUBA1A or autosomal recessive variants in PHOX2A." (PMID 38500555, 2023). "Variants in TUBB3 were previously found in Congenital fibrosis of the extraocular muscles CFEOM, but the specific TUBB3 E410K missense mutation has been recently associated with a more complex syndrome that, in addition to CFEOM, also shows KS and additional clinical features." (PMID 34502334, 2021). "TUBB2B and TUBB3-related β-tubulinopathies can also present as disorders of axon growth and guidance, causing additional anomalies in axons innervating the oculomotor muscles, resulting in an eye-movement disorder termed as congenital fibrosis of the extraocular muscles (CFEOM; MIM: PS135700)." (PMID 41153399, 2025).
cortical dysplasia (7 papers, 2014 to 2025). "Polymicrogyria or polymicrogyria-like cortical dysplasia and a simplified gyral pattern, which is common in TUBB2B and TUBB3 variants, have not been described in patients with TUBG1 variants so far." (PMID 29706637, 2018).
glioma (7 papers, 2015 to 2025). A benign or malignant brain and spinal cord tumor that arises from glial cells (astrocytes, oligodendrocytes, ependymal cells). "The optimal marker for this application is TUBB3, which is also found to be a marker for high-grade gliomas." (PMID 36900348, 2023). "In gliomas, TUBB3 expression seems to correlate with an increased malignancy, high proliferative rates, and poor prognosis." (PMID 33251771, 2021). "TUBB3 as a microtubule protein mainly expressed in cells of neuronal origin has been revealed as overexpressed in many cancers including gliomas." (PMID 33251771, 2021). "A majority of engrafted ASCL1-infected human glioma cells acquired neuron-like morphology and expressed the pan-neuronal marker TUBB3." (PMID 31212628, 2019). "Epothiolones have been shown to act on TUBB3-expressing glioma cells by inhibiting cell motility through cytoskeleton disruption, promoting tumor cell death by survivin down-regulation and by mediating therapeutic effects in preclinical models." (PMID 27579614, 2016). "Further experiments demonstrated that SATB2 is rarely expressed in glioma cells expressing the differentiation markers (GFAP, TUBB3, and GALC) in human GBMs." (PMID 33124191, 2020). "TUBB3 and VIM have been identified in some human glioma cell lines before." (PMID 33251771, 2021). "Consistent with U251, the time-course immunocytochemical analysis with neuronal markers DCX, TUBB3 and MAP2, showed that ASCL1 alone could also rapidly and efficiently reprogram U87 human glioma cells into neuron-like cells." (PMID 31212628, 2019). "However, no TUBB3-positive neuron-like cells was observed in the mouse brain injected with control GFP-infected human glioma cells." (PMID 31212628, 2019).
polymicrogyria (7 papers, 2018 to 2023). A developmental brain abnormality characterized by an excessive amount of small convolutions on the surface of the brain and cognitive dysfunction. "For instance, a E421K mutation in TUBB2B and a R262C mutation in TUBB3 both cause ocular motor dysfunction, whereas individuals with a T312M variant in TUBB2B and a R46G mutation in TUBB3 both present with multifocal polymicrogyria." (PMID 36875768, 2023). "This includes lissencephaly (TUBA1A), polymicrogyria (TUBA1A, TUBB2B, TUBB3), microcephaly (TUBB2B, TUBB3, TUBB5, TUBG1), and oculomotor disorders (TUBB2B, TUBB3)." (PMID 33137126, 2020). "The association between microcephaly, polymicrogyria and cerebellar agenesis prompted us to screen for tubulin genes (TUBA1A, TUBA8, TUBB2A, TUBB2B, TUBB3, TUBB4A, TUBB, TUBG1), which were all negative." (PMID 35162247, 2022).
bladder cancer (6 papers, 2018 to 2025). "ALDH1A1, a recognized diagnostic target overexpressed in bladder cancer, and its downstream target TUBB3 can be degraded to reduce invasion and proliferation, providing new avenues for diagnosis and therapy in advanced disease." (PMID 41153362, 2025). "It is also worthy to note that ALDH1A1 contributes to bladder cancer progression by increasing the expression of βIII-tubulin (TUBB3)." (PMID 35173149, 2022). "Clinical survival data suggest that TUBB3 expression correlates with poor prognosis in bladder cancer patients, indicating that ALDH1A1 and TUBB3 may serve as promising therapeutic targets." (PMID 40635786, 2025). "This prompted the suggestion that TUBB3 expression may contribute to the maintenance of CSCs in bladder cancer, which could account for why elevated TUBB3 is observed with more aggressive subtypes of bladder cancer." (PMID 35573698, 2022). "It was reported that ALDH1A1 could upregulate TUBB3 to promote bladder cancer progression." (PMID 35173149, 2022). "Notably, TUBB3 has been documented to be a downstream target of ALDH1A1 and can be positively regulated by ALDH1A1 in bladder cancer." (PMID 35173149, 2022).
colon cancer (6 papers, 2017 to 2022). "In colon cancer cells there was a positive correlation between upregulation of TUBB3 and snail showing that TUBB3 is functionally linked to the EMT process." (PMID 33171868, 2020). "The data presented in these studies demonstrate for the first time that downregulation of TUBB4B and upregulation of TUBB3 observed during EMT is crucial for establishing the mesenchymal character of colon cancer cells." (PMID 31375012, 2019). "Therefore, we focused on the role of TUBB4B downregulation and TUBB3 modulation in microtubule polymerization during EMT in colon cancer progression." (PMID 31375012, 2019).
glioblastoma (6 papers, 2017 to 2025). The most malignant astrocytic tumor (WHO grade IV). "While either SOX11 or ZIC1 promotes the expression of TUBB3/βIII-tubulin and induces a neuronal phenotype in U87 glioblastoma cells, the expression of ZIC1 greatly enhances the impact SOX11 has on TUBB3 expression and neuronal differentiation." (PMID 35573698, 2022). "Similarly, HIF1 and HIF2a interactions with overlapping HIF response elements within the TUBB3 3’UTR suppress and induce TUBB3 expression in glioblastoma in normoxia and hypoxia, respectively." (PMID 28677634, 2017).
ptosis (6 papers, 2020 to 2024). The drooping of the upper eyelid. "The clinical features of type 3 CFEOM3 caused by TUBB3 mutations vary from mild ptosis and restricted extraocular movement to severe ocular motility issues and central nervous system abnormalities." (PMID 38975553, 2024). "Subjects with ECEL1 variants display congenital distal arthrogryposis together with variably penetrant combinations of ptosis, strabismus, and ophthalmoplegia, similar to subjects with the TUBB3 R262H syndrome." (PMID 34652576, 2021). "TUBB3 R262C syndrome subjects have an isolated CFEOM3 eye phenotype, with variable limits of vertical and horizontal eye movements, with or without ptosis." (PMID 34652576, 2021).
Kallmann syndrome (5 papers, 2021 to 2024). Kallmann syndrome (KS) is a developmental genetic disorder characterized by the association of congenital hypogonadotropic hypogonadism (CHH) due to gonadotropin-releasing hormone (GnRH) deficiency, and anosmia or hyposmia (with hypoplasia or aplasia of the olfactory bulbs). "In present study, three patients with TUBB3 E410K and R262H variants (C21, C32 and C52) fitted the diagnostic criteria of Kallmann syndrome, confirmed the previous report results and suggested that TUBB3 gene may involve in the pathogenesis of Kallmann syndrome." (PMID 36494820, 2022). "The TUBB3 R262H syndrome includes CFEOM3, congenital facial weakness, intellectual disabilities, Kallmann syndrome, joint contractures, motor disabilities, and progressive peripheral neuropathy with onset in the first decade of life." (PMID 34652576, 2021). "Features of the TUBB3 E410K syndrome (CFEOM3A, MIM #600638) include CFEOM, bilateral CFP, developmental delay, progressive sensorimotor polyneuropathy, Kallmann syndrome, stereotyped midface hypoplasia, and in some cases, vocal cord paralysis, tracheomalacia, and cyclic vomiting." (PMID 33827624, 2021).
melanoma (5 papers, 2019 to 2023). A malignant, usually aggressive tumor composed of atypical, neoplastic melanocytes. "It has been discovered that TUBB3 inhibits migration by interfering with microtubule dynamics in malignant melanoma cells." (PMID 37752167, 2023). "Consistent with our 30 day in vivo phenotypic analysis, neuronal markers including Nestin, Tubb3, Gfap and Ngfr were upregulated in tumors, again a noted feature of human melanomas." (PMID 31685822, 2019). "Similar to the results in nude mice, Tomato+ cells in these tumors were positive for melanoma markers such as Sox10 and heterogeneously expressing melanocytic markers Dct and pigment, as well as neuronal markers Tubb3 and Nestin." (PMID 31685822, 2019). "In addition, most GFP+ melanoma cells now expressed Nestin, GFAP and Tubb3, reminiscent of human melanomas known to frequently express these neuronal markers." (PMID 31685822, 2019). "These melanoma cells lacked expression of neuronal markers Nestin, GFAP and Tubb3." (PMID 31685822, 2019).
Strabismus (5 papers, 2021 to 2024). A misalignment of the eyes so that the visual axes deviate from bifoveal fixation. "TUBB3 G82R [244G > A]: A de novo variant in a 5-year-old boy with axial hypotonia, moderate intellectual disability and strabismus." (PMID 37600020, 2023).
Alzheimer disease (4 papers, 2022 to 2025). A progressive, neurodegenerative disease characterized by loss of function and death of nerve cells in several areas of the brain leading to loss of cognitive function such as memory and language. "Additionally, AST4 expressed a high level of MAP3K5, MAPK10, and TUBB3, which are enriched in Alzheimer's disease–related pathways (hsa05010, P = 2.0 × 10−07)." (PMID 38091510, 2022). "The genes, which play a vital role in the TUBB3 (formation of beta-tubulin), FABP3 (regulates alpha-Synuclein uptake in dopaminergic neurons) and CALM1 (Calcium signal transduction pathway) in Alzheimer’s disease, were upregulated." (PMID 40520681, 2025). "In initial round of PPI search, I found UNC5C (netrin receptor) interaction with TUBB3 as strong PPI interactions, which is a non-tubulin family of protein involved in neuronal development and also associated with Alzheimer’s disease." (PMID 37466845, 2023).
microcephaly (4 papers, 2017 to 2022). A congenital or acquired developmental disorder in which the circumference of the head is smaller than normal for the person's age and sex. "Microtubule structure alterations as well as alterations of binding partners necessary for proper microtubule dynamics resulting from pathogenic variants in TUBA1A, TUBB2A, TUBB2B, TUBB3, TUBB5, TUBG1 and TUBA8 genes are also responsible microcephaly and microlissencephaly." (PMID 30340542, 2018).
pancreatic cancer (4 papers, 2017 to 2025). "Subsequently, in the BALB/c nude mice model of pancreatic cancer in situ, the use of star polymer loaded with TUBB3 (βIII-tubulin) siRNA for treatment can silence the expression of βIII-tubulin and inhibit the growth and metastasis of pancreatic tumors." (PMID 35269550, 2022). "Tubulin beta 3 class III (TUBB3), but not tubulin beta class I (TUBB) or tubulin beta 2 A-C class IIa, IIb, IIc (TUBB2A-C), plays critical roles in pancreatic tumor growth and metastasis." (PMID 39962586, 2025).
triple-negative breast carcinoma (4 papers, 2017 to 2023). An invasive breast carcinoma which is negative for expression of estrogen receptor (ER), progesterone receptor (PR), and human epidermal growth factor receptor 2 (HER2). "Higher expression of TUBB3 was detected in triple-negative breast cancer MDA-MB-231 cells compared to hormone-responsive MCF7 cells." (PMID 37065867, 2023). "Evaluation of class III β-tubulin expression (TUBB3), a marker associated with metastasis, revealed the following trends: higher expression of TUBB3 was detected in triple-negative breast cancer MDA-MB-231 cells compared to hormone-responsive MCF7 cells (P < 0.05)." (PMID 37065867, 2023). "We next examined the effects of TUBB3 on triple negative breast cancer (TNBC) growth and invasion." (PMID 32909943, 2020).
diabetes (3 papers, 2020 to 2026). "In NOD mice, although diabetes incidence was lower in males than in females, diabetic male mice displayed comparable loss of islet sympathetic innervation and reduced expression of Gap43, Tubb3, and Stmn2." (PMID 41243316, 2026). "We found that diabetes and FTO overexpression decreased mRNA level of Tubb3 in mice neural retina in a synergistic manner." (PMID 38297099, 2024).
epilepsy (3 papers, 2016 to 2022). A brain disorder characterized by episodes of abnormally increased neuronal discharge resulting in transient episodes of sensory or motor neurological dysfunction, or psychic dysfunction. "On the contrary, mutations in the TUBB3 gene cause epilepsy only in 5% of cases." (PMID 31269740, 2019). "EEG and clinical data of six epileptic patients from a cohort of 15 patients carrying mutations in TUBA1A, TUBB2B and TUBB3 tubulin genes are analyzed as well as a literature review on the role of these genes and epilepsy is reported with the aim to define a specific associated epileptic pattern." (PMID 31269740, 2019). "Mutations in TUBA1A (60%) and TUBB2B (74%) and TUBB3 (25%) genes are associated with epilepsy." (PMID 31269740, 2019). "Among patients described in literature carrying mutations in TUBA1A gene, epilepsy was reported in 28% (44/155), while it was described in 49% (19/39) of TUBB2B and in 5% (3/62) of TUBB3 mutated patients." (PMID 31269740, 2019). "Clinical and EEG data: six out of 15 patients presented epileptic seizures (40%) (three with TUBA1A gene mutation and three with TUBB2B gene mutation; none TUBB3 carrying gene mutation showed epilepsy)." (PMID 31269740, 2019). "Incidence of mutations associated with epilepsy is not significantly different among the tubulin domains for TUBA1A and TUBB2B genes, while in the TUBB3 gene, the C-domain does not show mutations related to epileptic features." (PMID 31269740, 2019).